CAPS2 (calcyphosine 2)
Synonyms: UG0636c06
Tractability: PROTAC: ubiquitination databases record sites on it.
Gene: Protein-coding gene on chromosome 12 (75,275,979 to 75,390,950, reverse strand). Ensembl gene ENSG00000180881.
Subcellular location (Human Protein Atlas): Nucleoli; Centrosome; Nucleoplasm; Vesicles
Gene Ontology:
Molecular function: calcium ion binding
Genetic constraint (gnomAD): Loss-of-function variants: 30 observed, 27.92 expected, observed/expected ratio (o/e) 1.07, 90% interval 0.8 to 1.46. The upper end of that interval is the gene's LOEUF score, 1.46, which puts it in group 6 of 6, group 1 being the genes least tolerant of losing a copy. Missense variants: 276 observed, 258.26 expected, observed/expected ratio (o/e) 1.07, 90% interval 0.97 to 1.18. Synonymous variants: 83 observed, 90.17 expected, observed/expected ratio (o/e) 0.92, 90% interval 0.77 to 1.11.
Homologues: Orthologues: chimpanzee CAPS2 (98% identical), macaque CAPS2 (85% identical), pig CAPS2 (80% identical), rabbit CAPS2 (80% identical), dog CAPS2 (78% identical), mouse Caps2 (71% identical), rat Caps2 (71% identical), guinea pig CAPS2 (57% identical), tropical clawed frog CAPS2 (33% identical), zebrafish caps2 (31% identical), Drosophila melanogaster TpnC73F (6% identical), Drosophila melanogaster TpnC41C (5% identical), and 1 more. Paralogues in human: EFCAB6 (15% identical), CAPSL (11% identical), CAPS (11% identical), PHF24 (9% identical), SPATA21 (6% identical).
Diseases named in the same sentence as CAPS2 in open-access papers:
CAPS2 is named in the same sentence as 14 diseases in open-access papers, as found by Europe PMC text mining. Sharing a sentence is not in itself a finding about the gene and the disease. The quoted sentences say what the papers report.
autism (8 papers, 2007 to 2025). Persistent deficits in social interaction and communication and interaction as well as a markedly restricted repertoire of activity and interest as well as repetitive patterns of behavior. "The human CAPS2 gene locus (7q31.32) is located within the autism susceptibility locus 1 (AUTS1) on chromosome 7q31–q33, one of several susceptibility loci for autism." (PMID 24923991, 2014). "We previously identified dex3, a rare alternative splice variant of CAPS2, which is overrepresented in patients with autism and is missing an exon 3 critical for axonal localization." (PMID 24923991, 2014). "We previously generated a mouse model CAPS2Δex3/Δex3 that expressed autism-associated CAPS2 isoform dex3 and revealed that dex3 mice showed the autistic-like behavioral phenotypes." (PMID 24923991, 2014). "In this report, we focused on the cellular and physiological phenotype in the cerebellum of a mouse line CAPS2Δex3/Δex3 expressing dex3, the same as a rare alternatively-spliced variant of human CAPS2 that was identified in some individuals with autism." (PMID 24923991, 2014). "The human CAPS2 gene is located within 7q31.32, mapping to the autism susceptibility locus 1 (AUTS1:7q31-q33)." (PMID 24287856, 2013). "The expression of an aberrant splicing variant of CAPS2 in some patients with autism has also been reported." (PMID 17428348, 2007). "In addition, the association of CAPS2 with autism has been suggested not only by the presence of copy number variations in the CAPS2 gene in autistic patients, but also by decreased transcription of CAPS2 in the brains of people with autism." (PMID 24923991, 2014). "CAPS2 promotes BDNF secretion, and its mutation is associated with autism and anxiety-like behavior." (PMID 28122057, 2017). "We recently reported that an aberrant, alternatively spliced CAPS2 mRNA that lacks exon 3 (CAPS2Δexon3) is detected in some patients with autism." (PMID 17428348, 2007). "Therefore, among the various mouse models of autism, the Caps2-KO mouse, which exhibit impairments in BDNF release, represents a suitable first target for evaluating body ownership using the rubber tail task." (PMID 31101876, 2019). "We previously showed that the expression of an exon 3-skipped (or -spliced out) form of CAPS2 (designated CAPS2-dex3), which is now known as a rare alternative splicing variant, is increased in a subgroup of patients with autism and is not properly transported into axons." (PMID 24923991, 2014). "Moreover, by comparing CAPS2 gene expression patterns between autism patients and healthy controls, it has been shown that the CAPS2-dex3 type, with deletion of exon 3 (111 amino acids) by rare alternative splicing, is abnormally increased in some autism patients." (PMID 24287856, 2013). "Taken together, these data not only point to a role for CAPS2 in regulating BDNF secretion, but also demonstrate how dysregulation of CAPS2 results in autism-related behaviors in rodent models and human patients." (PMID 41254423, 2025).
Anxiety (4 papers, 2007 to 2021). Intense feelings of nervousness, tension, or panic often arise in response to interpersonal stresses. "We then evaluated the effects of a MHb-specific CAPS2 knockdown on depression- and anxiety-like behavioral phenotypes." (PMID 33580180, 2021). "CAPS2 KO mice also manifested autistic phenotypes, including impaired social interaction, decreased exploratory behavior and increased anxiety in a novel environment, plus increased immobility time in FST8,12,45." (PMID 33580180, 2021). "The CAPS2 KO mice manifest decreased social interaction with cage mates, a hyperactivity in the home cage, a reduction in exploring, and increased anxiety in novel environments." (PMID 33580180, 2021). "Moreover, in an elevated plus maze test, CORT-treated Caps2 KO mouse group showed a tendency to decrease time spent in open arm compared with the other groups, thereby suggesting increased anxiety in Caps2 KO mice after chronic CORT treatment." (PMID 25754523, 2015). "We suggest that Caps2 KO mice have an altered endocrine response to CORT, while maintaining CORT-induced anxiety/depressive-like behavior." (PMID 25754523, 2015). "Together, these data suggest that selective reduction of MHb CAPS2 protein induces despair-like behavior, but not anxiety, anhedonia, and social dysfunction." (PMID 33580180, 2021). "Despite the defects in insulin and leptin release during CORT treatment, Caps2 KO mice did not exhibit heightened anxiety/depressive behavior compared with WT mice." (PMID 25754523, 2015). "For total center time, which reflects anxiety, CORT-treated mice showed lower values compared to untreated mice among both WT and Caps2 KO mice (Mann-Whitney U-test: WT untreated vs. WT CORT-treated, P < 0.005; Caps2 KO untreated vs. Caps2 KO CORT-treated, P < 0.006)." (PMID 25754523, 2015).
depression (2 papers, 2021 to 2026). "In the present study, we identified the distribution of CAPS2 in the MHb and its role in depression-related behavioral symptoms." (PMID 33580180, 2021). "Habenular CAPS2 expression was decreased in the rat chronic restraint stress model, mouse learned helplessness model, and showed tendency to decrease in depression patients who died by suicide." (PMID 33580180, 2021). "Indeed, in MDD and in animal models of depression, the MHb has been shown to exhibit marked downregulation of calcium-dependent activator protein for secretion 2 (CAPS2) and deficits in nicotinic acetylcholine receptor-mediated signaling." (PMID 41654494, 2026). "We next investigated whether the selective suppression of the MHb CAPS2 expression induced depression-related behaviors." (PMID 33580180, 2021). "CAPS2 gene was down-regulated in animal models of depression, and selective knockdown of CAPS2 in the MHb induced the despair-like behavior, which may be associated with dysregulation of DCV exocytosis reducing the neuronal activity of the IPN and monoaminergic neurons." (PMID 33580180, 2021). "CAPS2 expression level is decreased in the CRS rat model, LH mice model of depression, and tended to decline in human MDD, implicating a link for CAPS2 levels in depression." (PMID 33580180, 2021).
Obesity (2 papers, 2016 to 2025). Accumulation of substantial excess body fat. "For REBA, the Calcyphosine 2 (CAPS2) gene has been described to be involved in obesity regulation during embryonic pre-implantation in sheep." (PMID 39794685, 2025). "The genes within 2 Mb of the signal, include RP11-81H3.2, CAPS2, GLIPR1, GLIPR1L1, GRLPR1L2, and KRR1, none of which is an obvious candidate gene for involvement in obesity or T2D." (PMID 27623749, 2016).
diabetes (1 paper, 2025). "The precise relationship between CAPS2 (NLRP3) and diabetes is not yet fully understood; however, recent investigations suggest that NLRP3 and its associated inflammatory pathways may play a role in the pathogenesis of diabetes." (PMID 40296871, 2025). "Leeches may influence cellular immunity by modulating immune receptor activity, particularly through the activation of RGS10, CAPS2, and OPA1, thereby impacting the pathology of Type 2 Diabetes Mellitus (T2DM)." (PMID 40296871, 2025).
Insulin resistance (1 paper, 2025). Increased resistance towards insulin, that is, diminished effectiveness of insulin in reducing blood glucose levels. "CAPS2 may influence insulin resistance and beta cell dysfunction by regulating the release of inflammasomes and pro-inflammatory cytokines, such as IL-1β." (PMID 40296871, 2025).
lung carcinoma (1 paper, 2024). "The expression of CAPS2 is higher in lung cancer tissues when compared to normal lung tissues, and it is linked to the stage of the tumor, lymph node metastasis, and poor survival." (PMID 38791918, 2024). "CAPS2 (Calcyphosine 2) (average methylation 14%, p = 0.005) is overexpressed in lung cancer, where it promotes cell proliferation, migration, invasion, and metastasis by activating the ERK/MAPK and AKT signaling pathways." (PMID 38791918, 2024). "As such, CAPS2 can be used as a biomarker to monitor lung cancer progression following therapy." (PMID 38791918, 2024).
pancreatic disorders (1 paper, 2022). "We believe that this study provides much-needed insight regarding the pancreatic exocrine regulation by CAPS2 as a potential risk factor for lifestyle-related pancreatic disease." (PMID 36419930, 2022).
schizophrenia (1 paper, 2025). A major psychotic disorder characterized by abnormalities in the perception or expression of reality. "Taken together, these data suggest the possibility that BDNF Val66Met, together with altered CAPS2, htt, and kinesin function, contributes to schizophrenia." (PMID 41254423, 2025). "Notably, alterations in KIF13A and KIF13B expression, htt expression, and CAPS2, a secretory granule-associated protein implicated in BDNF-regulated exocytosis, have all been noted in patients with schizophrenia." (PMID 41254423, 2025).
cancer (2 papers, 2024). A tumor composed of atypical neoplastic, often pleomorphic cells that invade other tissues. "The findings from the CAPS1 and CAPS2 trials provide compelling evidence that dietary modification could play a crucial role in managing these side effects and perhaps even retard cancer progression." (PMID 38893112, 2024). "CAPS2 (Calcyphosine 2) (average methylation 26%, p = 0.005) and GLIPR1L2 (GLI pathogenesis-related 1) (average methylation 30%, p = 0.008), both were previously discussed in the group due to hypomethylation in PD-L1 high-expressing carcinomas." (PMID 38791918, 2024).
tumor (2 papers, 2016 to 2024). "Similar to CAPS1, CAPS2 protein expression was significantly decreased in the tumor tissues compared with peritumoral tissues." (PMID 27689999, 2016). "Hypomethylated genes and promoters in this group seem to lose their tumor-suppressing effects (IFITM3 and GLIPR1L2) and perhaps show a reduction in oncogene activity (CAPS2)." (PMID 38791918, 2024).
CAPS2 also shares sentences with these, for which no sentence is quoted: autism spectrum disorder (1 paper); lymph node metastasis (1); type 2 diabetes mellitus (1).